JAK2 (Janus kinase 2)
Diseases named in the same sentence as JAK2 in open-access papers (continued):
Sharing a sentence is not in itself a finding about the gene and the disease.
breast cancer (continued). "Mechanistically, we demonstrated that MUC16-Cter results in nuclear translocation of JAK2, which preferentially phosphorylates histone-3 and up regulates stemness-specific genes such as LMO2 and NANOG, which was further validated using Jak2 deficient (Jak2−/−) mouse mammary tumor cells." (PMID 25691062, 2015). "Therefore, pSTAT5 promotes early lesion progression to cancer in both nulliparous and parous mice, and chemoprevention targeting Jak2/pSTAT5 may lower the risk of breast cancer in both nulliparous and parous women." (PMID 24381245, 2013). "Here, we demonstrated that PTPRO suppresses breast cancer lung metastasis by targeting the JAK2–YAP axis." (PMID 40016288, 2025). "We investigated the expression pattern of the JAK-STAT signaling pathway in these four breast cancer cell lines and observed high activation of JAK2 and STAT3 in TNBC cell lines." (PMID 40199813, 2025). "Higher CHEK2 and JAK2 expression have been correlated with better survival among patients with rectal adenocarcinoma, lung squamous cell carcinoma, breast cancer, ovarian cancer and several other cancer types." (PMID 40177144, 2025). "These comprehensive findings provide a sufficient theoretical basis for further experimental verification of the role of JAK2/STAT3 axis in the anti-breast cancer mechanism of RT." (PMID 40351419, 2025). "CD169+ macrophages exert differential effects, they mediate better outcomes and anti-metastatic actions in breast cancer, but facilitate tumor immune escape via JAK2 signaling." (PMID 39875968, 2025). "Statement of Retraction: Homeodomain-containing gene 10 contributed to breast cancer malignant behaviors by activating Interleukin-6/Janus kinase 2/Signal transducer and activator of transcription 3 pathway." (PMID 40267127, 2025). "Research by Yujie Li has shown that DLGAP5 regulates breast cancer cell proliferation, migration, invasion, and the cell cycle via the JAK2/STAT3 signaling axis." (PMID 40406126, 2025). "Homeodomain-containing gene 10 contributed to breast cancer malignant behaviors by activating Interleukin-6/Janus kinase 2/Signal transducer and activator of transcription 3 pathway." (PMID 40267127, 2025). "This suggests that Osthole possesses the ability to inhibit both the proliferation and metastatic capabilities of breast cancer cells, primarily through the suppression of the JAK2/STAT3 signaling cascade." (PMID 40978029, 2025). "Data from patient, animal and cell-based models collectively demonstrated that PTPRO suppresses breast cancer lung metastasis by inhibiting JAK2–YAP dephosphorylation." (PMID 40016288, 2025). "Mechanistically, PTPRO suppresses breast cancer lung metastasis by dephosphorylating JAK2 and inhibiting the JAK2–YAP pathway." (PMID 40016288, 2025). "MUC16 has been reported to take part in breast cancer progression and metastasis when overexpressed due to its influence on cell cycle and survival through the JAK2/STAT3 pathway." (PMID 39723380, 2024). "Upregulation of JAK-2 in breast cancer enhances survival and growth of cancer cell by regulating of cell division and apoptosis through overexpression of Bcl-2 family members and cyclin." (PMID 38827789, 2024). "The JAK2/STAT3 pathway plays an important role in the deterioration of breast cancer, including proliferation and metastasis." (PMID 38686052, 2024). "The mechanism of metochalcone against breast cancer depended on the induction of SASP via deactivation of the JAK2/STAT3 pathway, highlighting the potential of chalcone in senescence-inducing therapy against carcinomas." (PMID 38686052, 2024).
breast cancer (continued). "Conversely, vascular endothelial growth factor‐alpha (VEGF) upregulates the expression of Myc and Sox2 through its receptor VEGFR‐2, thereby enhancing the self‐renewal capacity of breast cancer stem cells via the JAK2/STAT3 pathway." (PMID 39558881, 2024). "Sodium propionate demonstrates anticancer effects by modulating the JAK2/STAT3/ROS/p38 MAPK signaling pathway in breast cancer xenografts in mice." (PMID 39717276, 2024). "One of the most common mechanisms of traditional Chinese medicine and natural products against breast cancer is modulation of the JAK2/STAT3 pathway." (PMID 38686052, 2024). "Functional analysis revealed that CCT2 promoted breast cancer growth and metastasis through activation of the JAK2/STAT3 signaling pathway." (PMID 39079960, 2024). "Experimental studies have shown that phosphorylation of STAT5 regulates the biological functions of prostate and breast cancer cells, and the JAK2/STAT5 cascade appears to be the only pathway activated by PRL in prostate." (PMID 38341429, 2024). "MAPK1 and JAK2 demonstrated the strongest specificity and the best staining in breast cancer tissues." (PMID 39867914, 2024). "Our study first demonstrated the anti-tumor effects of TEC against breast cancer and lung cancer via inhibition of the JAK2/STAT3 signaling and further revealed the potential role of metochalcone in restricting tumor growth in vivo." (PMID 38686052, 2024). "Research showed that pentadecanoic acid suppressed the invasiveness of malignant breast cancer cell lines through the inhibition of Janus kinase 2/signal transduced and activator of transcription 3 (JAK2/STAT3)." (PMID 38335180, 2024). "In breast cancer, the PPARγ ligand pioglitazone has been shown to act as a tumor suppressor via the JAK2/STAT3 signaling axis." (PMID 39770941, 2024). "Molecular docking results indicated that JAK2 was a potential target of PSP in breast cancer, and KEGG analysis showed that the JAK-STAT pathway was enriched." (PMID 38872110, 2024). "In conclusion, our research elucidates the critical function of CCT2 in breast cancer progression, primarily via the initiation of the JAK2/STAT3 signaling cascade." (PMID 39079960, 2024). "Prior research has demonstrated that TM4SF1 has the ability to initiate the JAK2/STAT3 signaling pathway in breast cancer, hence facilitating the spread of breast cancer to several target organs." (PMID 38762481, 2024). "In light of hypoxia, the Exos with higher levels of lncRNA SNHG1 and mir-216b-5p are released form breast cancer cells and the uptake of these Exos promotes angiogenesis in human ECs via Janus kinase 2 (JAK2)." (PMID 38360641, 2024). "Due to the conclusive role of the JAK-2 signaling pathway in breast cancer, various researches were conducted on breast cancer therapy through targeting JAK-2 by gene inhibitors." (PMID 38827789, 2024). "Inhibition of JAK2 blocked the growth of human basal-like breast cancer cell lines in vitro and in vivo in mouse xenograft models." (PMID 38297352, 2024). "In summary, our in vitro data suggest that GluOC accelerates the metastasis of MDA-MB-231 breast cancer cells by promoting ROCK1/MYPT1/MLC2 signalling, and by promoting breast cancer cell proliferation via the ROCK1/JAK2/PIK3CA/AKT signalling pathway." (PMID 39054484, 2024). "We concluded that GluOC promotes the proliferation and apoptosis of MDA-MB-231 breast cancer cells through the ROCK1/JAK2/PIK3CA signalling pathway." (PMID 39054484, 2024). "The JAK2/STAT3 signaling pathway is required for growth of CD44(+) CD24(−) stem cell-like breast cancer cells, particularly in basal-like breast cancers and is independently associated with breast cancer metastasis and poor prognosis." (PMID 36635351, 2023).
breast cancer (continued). "JAK2/STAT3 activation promotes breast cancer cell growth, survival, and metastasis via EMT induction and chemotherapy resistance." (PMID 36674719, 2023). "About half of them in BL1 and BL2 were overlapping, such as LYN, JAK2, SYK, and EGFR, which were reported to be associated with the aggressiveness of breast cancer, particularly in TNBC." (PMID 36672350, 2023). "MiR-101 targeted Janus kinase 2 (JAK2) in inhibiting proliferation and promoting apoptosis of breast cancer cells." (PMID 37508580, 2023). "In contrast, JAK2 inhibitor AG490 can downregulate the expression of GRAMD1B in breast cancer MDA-MB-231 cells, suggesting that JAK/STAT signaling controls the expression of GRAMD1B in breast cancer cells." (PMID 37237509, 2023). "JAK2 mediates multiple aspects of cytokine signaling, leading to supporting survival and promoting proliferation in breast cancer and B-cell leukemias and lymphomas." (PMID 37147297, 2023). "Previous studies have emphasized the crosstalk between PI3K, HER2, JAK2, and IL-8 signaling targets for metastatic breast cancer therapies." (PMID 38028209, 2023). "Studies in the literature have focused on mRNA expression of JAK1 and JAK2 and have concluded high expression predicts better outcome in breast cancer." (PMID 37199043, 2023). "The scores for both cytoplasmic and stromal JAK2 differed significantly across molecular subtypes of breast cancer (p < 0.001)." (PMID 37199043, 2023). "Behera and colleagues reported that osteopontin can bind αvβ3 integrin and induce JAK2/STAT3 activation in human breast cancer cells." (PMID 37614232, 2023). "Pentadecanoic acid is a JAK2/STAT3 signaling inhibitor in breast cancer cells and an anti-biofilm agent." (PMID 38005278, 2023). "JAK2 inhibitors have been created as specific treatments for breast cancer, including ruxolitinib and fedratinib." (PMID 37711177, 2023). "Increased MUC16 expression in breast cancer also promotes cell cycle progression (G2-M) and cell survival via JAK2/STAT3 signaling pathway." (PMID 36918912, 2023). "Prolactin binding to the prolactin receptor (PRLR) can activate the transcription factor STAT5, thus, we examined the association between plasma prolactin and breast cancer risk by tumor expression of PRLR, STAT5, and the upstream kinase JAK2." (PMID 36882838, 2023). "Further, it has been explored that C15:0 has an inhibitory effect on the IL-6-induced JAK2/STAT3 signaling pathway in human breast carcinoma cells, considering C15:0 as a promising therapeutic strategy to treat human cancers." (PMID 37432205, 2023). "LncRNA associated with breast cancer brain metastases (lnc-BM) is significantly upregulated in brain metastasis and influences TAM recruitment by inducing the production of CCL2 via JAK2/STAT3 pathway activation in cancer cells." (PMID 35202089, 2022). "JAK2, BCl-2, and surviving are direct targets of miR-204 in breast cancer, and the opposite expression pattern of miR-204-JAK2 has been reported in NSCLC." (PMID 35087589, 2022). "Because of the crucial oncogenic role of the JAK2 pathway in breast cancer, several studies were conducted on the treatment of breast cancer by targeting JAK2 using JAK2 inhibitors." (PMID 35269680, 2022). "Numerous recent reports have shown that BA effectively inhibits lung cancer, melanoma, and breast cancer cell growth by repressing JAK2/STAT3 pathway." (PMID 36567856, 2022). "Consistent with the previously published results for breast cancer cells, nintedanib reduced the phosphorylation of JAK2 and STAT3 in senescent HDFs." (PMID 36055997, 2022). "Previous studies reported that overexpression of JAK2 in breast cancer promotes cancer cell survival and growth by modulating cell proliferation and apoptosis, partly through the upregulation of cyclin D1 and Bcl-2 family members, such as Bcl-xL and Bcl-2." (PMID 35269680, 2022).
breast cancer (continued). "Previous studies reported that overexpression of SOCS3 suppresses JAK2/STAT3-signaling activation thus inhibiting the JAK2/STAT3-mediated EMT in breast cancer." (PMID 35719940, 2022). "The BMPR1A nonsynonymous SNV (rs55932635) was identified in one of 56 BRCA-negative breast cancer patients in Puerto Rico, while the JAK2 nonsynonymous SNV (rs200018153) was found in one of 1487 acute myeloid leukaemia (AML) patients in the United States." (PMID 35954343, 2022). "A previous study showed that dual inhibition of PI3K/mTOR in BEZ235-resistant breast cancer cells triggered a positive feedback response and activated the JAK2/STAT5 pathway, resulting in increased IL-8 secretion and drug resistance." (PMID 33431808, 2021). "Recent researches indicated that amplification of chromosome 9p24.1 gave rise to activation of JAK2 signaling and overexpression of PD-L1 expression in breast cancer and lymphoid malignancies." (PMID 34045609, 2021). "MSM is reported to decrease the invasiveness of cells via modulation of vascular endothelial growth factor (VEGF) in breast cancer cells as well be tested in combinational therapy with Janus kinase 2 (Jak2) inhibitor in bladder cancer." (PMID 32562081, 2021). "At the same time, it has been confirmed that miR-101 directly increases breast cancer cell apoptosis by reducing the expression of Janus kinase (Jak2)." (PMID 34658308, 2021). "Our observations also provide first evidence to support future testing of a novel combination therapy for metastatic triple-negative and HER2-enriched breast cancers through simultaneous inhibition of JAK2 and TrkA kinase activities." (PMID 34066153, 2021). "PVT1 is a long noncoding RNA that is commonly overexpressed in breast cancer and has been implicated in the regulation of MYC oncogene, while JAK2 is a tyrosine kinase activating cancer-driving JAK/STAT signaling pathway." (PMID 34439480, 2021). "In conclusion, Que plays a synergistic role in killing breast cancer cells and promoting apoptosis by regulating the expression of IFNγ-R, p-JAK2, p-STAT1 and PD-L1 in the JAK/STAT1 signaling pathway and promoting the regulation of γδ T cells." (PMID 34838003, 2021). "So, the JAK2/STAT3 in CSC is a potential target for developing a successful strategy to improve breast cancer patients’ therapeutic outcomes." (PMID 33672756, 2021). "In breast cancer cells, activation of STAT3 via the IL-6/JAK2 cascade causes suppression of Bax/Bcl-2-associated caspase-dependent apoptosis." (PMID 34488773, 2021). "For example, co-overexpression of Janus kinase 2 and signal transducer and activator of transcription 5a was shown to affect mammary cancer cells via the epithelial–mesenchymal transition-pathway." (PMID 33803354, 2021). "A combinational therapy of MSM (200 mM) and tamoxifen was reported to inhibit breast cancer tumor growth and metastasis, both in vitro and in vivo by modulation of Jak2 and transducer and activator of transcription 5b (STAT5b) pathway." (PMID 32562081, 2021). "For example, the JAK2/STAT3 pathway is prominent in the progression of ovarian cancer, and it has been proven to be associated with metastasis in breast cancer." (PMID 34765550, 2021). "PRL in breast cancer cells via PRLR/JAK2 can also induce phosphorylation of ERBB2/HER2, which in turn activates the downstream RAS/MEK/ERK pathway required for ERα phosphorylation." (PMID 34572912, 2021). "Previous studies suggested that Jak2 induction of Jak2 activity upstream of STAT3 in breast cancer cells is a crucial step for the estrogen (ER)-dependent progression of cancer." (PMID 34833950, 2021). "The ERK/MAPK and JAK2/PI3K signaling cascades in breast cancer cells can be activated by α7-nAChR activation, while α9-nAChR overexpression is observed in tumor tissues compared with adjacent normal tissues." (PMID 34899291, 2021). "For example, lnc-BM promotes the JAK2/STAT3 pathway to facilitate brain metastasis in breast cancer." (PMID 34765550, 2021).
breast cancer (continued). "First, for some recurrent mutations, such as those from CTNNB1, CSF1R, JAK2, HRAS, and RUNX1, an exhaustive literature search showed that the clinical significance in breast carcinoma has rarely been addressed." (PMID 34203389, 2021). "In the current study the apoptosis-inducing and anti-proliferative effects of Naringenin together with cyclophosphamide were studied in breast cancer cells and the participation of JAK2/STAT3 pathway was investigated." (PMID 33680016, 2020). "Ruxolitinib is a tyrosine kinase inhibitor that selectively inhibits Jak1 and Jak2 signaling and is being evaluated in multiple breast cancer clinical trials for its chemotherapeutic effects." (PMID 33019728, 2020). "Another study showed that miR-101 suppressed proliferation and promoted apoptosis in breast cancer cells by targeting Jak2." (PMID 32645833, 2020). "This study proposes the use of pentadecanoic acid as a novel JAK2/STAT3 inhibitor in breast cancer therapy." (PMID 32503225, 2020). "A recent study revealed that TM4SF1 coupled with DDR1 was shown to promote cancer stem cell traits and metastatic reactivation and by PKCα-dependent JAK2/Stat3 signalling in breast cancer." (PMID 33153498, 2020). "AG490 is a tyrosine kinase inhibitor that inhibits the Jak2 pathway in breast cancer cells in vitro by decreasing the phosphorylation of Stat3." (PMID 33019728, 2020). "JAK2/STAT3 signaling has been reported to be responsible for the maintenance of CD44+/CD24− stem like-cell populations isolated from human breast cancer cells." (PMID 32503225, 2020). "Since IL-6 exerts its influence on breast cancer cells via JAK2/STAT3 pathway, the inhibitory effect of Nar-Cpm combination on IL-6 influence further proves its ability to target JAK2/STAT3 signaling pathway." (PMID 33680016, 2020). "Activation of p38 MAPK and c-Jun N-terminal kinase (JNK) while suppressing Janus kinase-2 (JAK2) was noted in breast cancer cells." (PMID 32245062, 2020). "In another study, treatment with a pan-JAK inhibitor was shown to inhibit the viability of basal-like cell lines, and a JAK2 inhibitor was shown to reduce tumor growth in murine cell line and primary breast cancer xenograft models." (PMID 32328465, 2020). "Recently, we reported that tubulosine inhibited JAK2/STAT3 signalling in IL‐6‐induced breast cancer." (PMID 32558259, 2020). "The recruited macrophages secreted IL-6 and oncostatin M, which activated the Lnc-BM/JAK2/STAT3 pathway in breast cancer cells." (PMID 32083005, 2020). "For example, Lnc-BM (a lncRNA related to breast cancer brain metastasis), binds to JAK2 and modulates its kinase activity through the Lnc-BM/JAK2/STAT3/ICAM1 pathway." (PMID 32083005, 2020). "Blockade of GHR using neutralizing antibody or pharmacological inhibition of JAK2/STAT5 inhibits ABCG2 promoter activity suggesting that GHR regulates ABCG2 through JAK2/STAT5 signaling mechanism in ER−ve breast cancers." (PMID 30617282, 2019). "We found that PAK1 interacts with JAK2 and Stat3, and then activates Stat3 signaling to support mammosphere formation and stemness of breast cancer cells." (PMID 31658701, 2019). "Since there is accumulating interest in understanding PDGFRβ-mediated resistance mechanisms in various cancers, in this study we sort to investigate its role in resistance to JAK2 inhibition in breast cancer." (PMID 30777101, 2019). "Further, protection of endocrine-resistant breast cancer from ruxolitinib, a JAK2-inhibitor, was reported to coincide with GHR expression." (PMID 32382711, 2019). "Signaling via JAK2/STAT3 is a critical regulatory component in carcinogenesis in breast cancer related to obesity." (PMID 31380268, 2019). "L-dopa was recently reported to suppress cellular growth via down-regulation of prolactin-mediated JAK2/STAT5A in breast cancer cells 50, and carbidopa was reported to be an aryl hydrocarbon receptor agonist and to suppress the growth of pancreatic cancer." (PMID 31598163, 2019).